FABP5 (fatty acid binding protein 5)
Diseases named in the same sentence as FABP5 in open-access papers (continued):
Sharing a sentence is not in itself a finding about the gene and the disease.
multiple sclerosis (4 papers, 2023 to 2025). A progressive autoimmune disorder affecting the central nervous system resulting in demyelination. "We previously showed that the loss of either Fabp5 or calnexin causes resistance to the induction of experimental autoimmune encephalomyelitis (EAE) in mice, an animal model of multiple sclerosis (MS)." (PMID 39273210, 2024). "Remarkably, both calnexin-deficient and Fabp5-deficient mice are resistant to the induction of experimental autoimmune encephalomyelitis (EAE), an animal model of CNS inflammation including multiple sclerosis (MS)." (PMID 39273210, 2024). "In addition, oligodendrocytes in Krabbe disease and the multiple sclerosis model show an abnormal localization of FABP5 in the mitochondria, leading to the formation of large pores in the mitochondrial outer membrane." (PMID 38069360, 2023).
non-small cell lung carcinoma (4 papers, 2019 to 2024). A group of at least three distinct histological types of lung cancer, including non-small cell squamous cell carcinoma, adenocarcinoma, and large cell carcinoma. "Targeting GPLD1 has been found to inhibit the proliferation of non-small cell lung cancer cells mediated by p38 MAP kinase Knockdown or silencing of FABP5 has been shown to reduce the proliferation and invasiveness of PC cells in vitro and reduce tumor growth and metastasis in vivo." (PMID 37275878, 2023).
oral squamous cell carcinoma (4 papers, 2012 to 2024). "In oral squamous cell carcinoma, FABP5 regulates MMP-9 expression and tumor invasion." (PMID 34685761, 2021). "In cancer cells, FABP5 increases cell proliferation and invasiveness, as recently demonstrated in oral squamous cell carcinoma where its expression may be HPV-related." (PMID 22673103, 2012).
renal cell carcinoma (4 papers, 2018 to 2026). "Renal Cell Carcinoma (RCC): FABP5 is upregulated in RCC tissues and cell lines, and it is positively correlated with the progression of RCC." (PMID 40717587, 2025). "Upon ferroptosis induction, FABP5 concentrated at the cell surface in HT-1080 as well as in tested renal cell carcinoma lines, which are highly sensitive to ferroptosis." (PMID 38653992, 2024).
viral infection (4 papers, 2017 to 2024). "We found that there was a reduction of both Krt10 and Fabp5 RNA levels in the MmuPV1-induced tail tumors 21 days after viral infection." (PMID 34343212, 2021). "This study advances our understanding of FABP5 gene regulation and may open up new therapies for the treatment and/or prediction of recurrent exacerbations that are triggered primarily by bacterial and viral infections and are associated with increased airway inflammation." (PMID 28542209, 2017). "Also, cutaneous CD8+ TRM cells lacking Fabp4/Fabp5 in a mouse model were significantly reduced in their ability to resist cutaneous viral infections." (PMID 38596682, 2024).
acute myeloid leukemia (3 papers, 2023 to 2024). Acute myeloid leukemia (AML) is a group of neoplasms arising from precursor cells committed to the myeloid cell-line differentiation. "In acute myeloid leukemia cells, lycorine bound to fatty acid binding proteins 5 (FABP5), reducing triglyceride production and consequently increasing apoptotic rates." (PMID 39245716, 2024). "Bioinformatics analysis revealed that upregulation of FABP5 expression facilitates acute myeloid leukemia (AML) cell viability, protects AML cells from apoptosis." (PMID 38572428, 2024).
asthma (3 papers, 2015 to 2022). "However, ROC analyses showed poor diagnostic performance of sputum and NLF FABP5 for predicting asthma." (PMID 26020772, 2015). "Proteomic analysis of the 21 sputum samples revealed significant up-regulation of FABP5 gel spots in Asthma+AR group when compared to AR." (PMID 26020772, 2015). "The validation of FABP5 levels in all NFL samples revealed a similar pattern in the asthma and the control groups to that detected in the sputum analysis." (PMID 26020772, 2015). "The evidence we obtained of the role of FABP5 in asthmatic inflammation in airways needs to be confirmed in further studies on more severe asthma patients and larger groups." (PMID 26020772, 2015). "As with FABP5 values above, ROC analyses showed poor diagnostic performance of CysLT and VEGF for predicting asthma in the applied study population." (PMID 26020772, 2015). "FABP5 may contribute to the airway remodeling and inflammation in asthma by fine-tuning the levels of CysLTs, which induce VEGF production." (PMID 26020772, 2015). "Our findings indicate that FABP5 may contribute to the airway remodeling and inflammation in asthma by inducing VEGF production." (PMID 26020772, 2015).
autism spectrum disorder (3 papers, 2014 to 2022). A spectrum of developmental disorders that includes autism, and Asperger syndrome. "As for the role of FABP5 in the pathogenesis of schizophrenia and autism spectrum disorder (ASD), further studies have proved that disturbances in brain-expressed FABP5 could result in a proportion of psychiatric illnesses." (PMID 35445019, 2022). "Furthermore, we identified and reported several rare non-synonymous polymorphisms of the brain-expressed genes FABP3, FABP5 and FABP7 from schizophrenia and autism spectrum disorder (ASD), diseases known to part share genetic architecture." (PMID 25027319, 2014).
experimental autoimmune encephalomyelitis (3 papers, 2023 to 2024). An autoimmune demyelinating disease of the central nervous system that is produced experimentally in animals by the injection of homogenized brain or spinal cord in Freund's adjuvant. "Our studies using FABP5−/− mice confirm that FABP5 deficiency protects mice from the development of experimental autoimmune encephalomyelitis (EAE) by favoring Treg differentiation and function." (PMID 36765614, 2023). "A similar mechanism has been proposed for the protective effect of FABP5 inhibition in models of experimental autoimmune encephalomyelitis (EAE)." (PMID 37688656, 2024).
Hepatic fibrosis (3 papers, 2023 to 2024). The presence of excessive fibrous connective tissue in the liver. "A subset of macrophages expressing SPP1, GPNMB, FABP5, and CD63 have also recently been identified in pulmonary and hepatic fibrosis associated with scar formation." (PMID 38902328, 2024).
Nonalcoholic fatty liver disease (3 papers, 2012 to 2024). "Dysregulation was established for FABP3 in cardiovascular disorders, FABP1, FABP2, FABP4 and FABP5 in non-alcoholic fatty liver disease and FABP5 and FABP7 in cancer." (PMID 30386187, 2018). "Sequencing analysis of liver transcriptomes infected with different H. pylori strains revealed that “Nonalcoholic fatty liver disease” and “PPAR signaling pathway” were enriched according to KEGG enrichment analysis, and Fabp5 expression was significantly higher in the Cag A- groups." (PMID 39075482, 2024).
oral cancer (3 papers, 2022 to 2023). "Another study reported that the overexpression of FABP5 in oral cancer cells enhances cell proliferation and invasiveness by increasing the expression of MMP-9, while the knockdown of FABP5 using shRNA significantly inhibits the activity of MMP-9." (PMID 35445019, 2022). "In addition to PCa, FABP5 has been suggested as a biomarker for bladder and oral cancer, while other members of the family have been found frequently up-regulated in various cancers." (PMID 36553191, 2022).
ovarian carcinoma (3 papers, 2019 to 2025). A malignant neoplasm originating from the surface ovarian epithelium. "Ovarian Cancer: In ovarian cancer, FABP5 interacts with TAGLN2, promoting TAGLN2 cell surface localization and its role in activated CD8 + T cells." (PMID 40717587, 2025). "Regarding therapy resistance, FABP4 enhances mitochondrial β-oxidation to reduce apoptosis in ovarian cancer, and FABP5 promotes chemoresistance in HCC via the HIF-1α pathway." (PMID 40717587, 2025). "A recent study reported that ovarian cancer cell lines with a high ratio of intracellular lipid binding proteins CRABP2/FABP5, involved in retinoic acid delivery from the cytoplasm to nucleus were growth inhibited by 7 days ATRA (7 μM) treatment." (PMID 30621740, 2019). "Notably, the present extracellular flux analysis showed that the pharmacological inhibition of FABP4, FABP5, and PPARγ significantly ameliorated the reduced maximum respiration in ovarian carcinoma cell lines without affecting basal respiration." (PMID 40429934, 2025).
prostatic hyperplasia (3 papers, 2008 to 2020). "Ke and colleagues found that the expression of both FABP5 and PPARγ, but not PPARβ/δ, increases in PCa cell lines compared to benign cell lines and prostatic hyperplasia tissues, and that the cytoplasmic levels of FABP5 correlate with nuclear immunointensity of PPARγ in PCa tissues." (PMID 33352874, 2020).
pulmonary fibrosis (3 papers, 2023 to 2024). Chronic progressive interstitial lung disorder characterized by the replacement of the lung tissue by connective tissue, leading to progressive dyspnea, respiratory failure, or right heart failure. "The FABP5 gene encodes for fatty acid binding protein that is responsible for lipid trafficking metabolism and has been shown to aggravate pulmonary fibrosis through the Wnt-β-catenin pathway." (PMID 39682753, 2024). "Specifically, we identified an AM population with potential profibrotic function and Fabp5 and Gpnmb expression; targeting this population may help to provide therapeutic effect for pulmonary fibrosis." (PMID 37771586, 2023). "CD9+TREM2+ macrophages expressing GPNMB, SPP1, FABP5, and CD63 were reported in murine and human pulmonary fibrosis, enriched at the edges of scars." (PMID 37756565, 2023).
schizophrenia (3 papers, 2014 to 2022). A major psychotic disorder characterized by abnormalities in the perception or expression of reality. "In contrast to postmortem brains, FABP5 levels were lower in drug-naive schizophrenia derived peripheral lymphocytes." (PMID 25027319, 2014). "In postmortem brains, we detected altered mRNA expression levels of FABP5 in schizophrenia, and of FABP7 in ASD and altered FABP5 in peripheral lymphocytes." (PMID 25027319, 2014). "These combined data imply aberrant expression of FABP7 and FABP5 genes in the brains and/or lymphocytes of schizophrenia and ASD sufferers, suggesting a pathophysiological role for these genes." (PMID 25027319, 2014). "First, we found elevated FABP5 mRNA in the prefrontal cortex of schizophrenia postmortem brains." (PMID 25027319, 2014). "Current intriguing questions would focus on how upregulation of FABP5 and FABP7 in schizophrenia derived postmortem brains and upregulation of FABP7 in autism derived postmortem brains are associated with disease." (PMID 25027319, 2014). "If so, it would be feasible to investigate the use of lowered FABP5 protein and DHA levels in the blood as biological markers for schizophrenia." (PMID 25027319, 2014). "In this study, we performed comprehensive analyses of FABP7, FABP5 and FABP3, in the context of psychiatric illnesses, particularly schizophrenia and ASD." (PMID 25027319, 2014). "FABP5 is involved in acoustic startle response and performance of prepulse inhibition (PPI), a deficit of which is a biological marker for psychiatric illnesses such as schizophrenia and bipolar disorder." (PMID 35445019, 2022). "In another study, resequencing analysis of FABP3, FABP5 and FABP7 from an ASD cohort identified several rare non-synonymous polymorphisms, some of which were also seen in schizophrenia." (PMID 25027319, 2014). "Interestingly, we found that expression of FABP5 and FABP7 correlated tightly in both schizophrenia and control subjects, although the biological implications of this observation are unknown." (PMID 25027319, 2014).
Sjögren syndrome (3 papers, 2011 to 2022). "FABP1 has been suggested as a marker of renal failure, FABP3 as a marker of myocardial infarction, and FABP5 has lately been debated as a diagnostic marker for Sjögren’s syndrome." (PMID 32272779, 2020).
skin tumors (3 papers, 2023 to 2024). "Additionally, FABP5 plays a significant role in skin tumors; suppressing FABP5 or S100A9 expression impedes the proliferation and migration of cutaneous squamous cell carcinoma cells via the NF-κB pathway." (PMID 38596682, 2024).
squamous cell carcinoma (3 papers, 2015 to 2024). A carcinoma arising from squamous epithelial cells. "Furthermore, they found that the CRABP1, CRABP2, and FABP5 proteins were overexpressed in both benign papillomas and malignant squamous cell carcinomas (SCCs)." (PMID 26503156, 2015).
tongue cancer (3 papers, 2009 to 2023). A malignant neoplasm affecting the tongue. "Researchers found expression of FABP5, coding epidermal fatty acid binding protein (E-FABP-GenBank Accession), upregulated in primary tongue carcinomas." (PMID 19638242, 2009). "Besides, the cytoplasmic staining for FABP5 was increased in tongue carcinoma patients with advanced T-stage and clinical stage, implicating that FABP5 might be a pathological marker." (PMID 37927468, 2023). "further found abnormal expressions of FABP4 and FABP5 in tongue carcinoma, whereas only FABP5 was expressed in normal tongue epithelial cells, which showed a higher expression level in injured and cancer tissues." (PMID 36185215, 2022).
uveal melanoma (3 papers, 2021 to 2025). A melanoma derived from melanocytes of the uveal tract. "Furthermore, it was shown that FABP5 expression was positively correlated with progression-associated clinicopathological factors and poor prognosis in uveal melanoma (UVM), suggesting that FABP5 may be a possible oncogene and prognostic marker in patients with UVM." (PMID 39940783, 2025). "Fatty Acid Binding Protein 5 (FABP5) is highly correlated with complement signaling in uveal melanoma, and it promotes CD8+ T cell infiltration." (PMID 33869223, 2021).
Anxiety (2 papers, 2014 to 2021). Intense feelings of nervousness, tension, or panic often arise in response to interpersonal stresses. "Although the test anxiety caused deregulation of more salivary proteins in the control group than in the odor one, in the former, only α-amylase was increased, while α-amylase and FABP5 were present in higher amounts in the latter." (PMID 33919012, 2021). "The Fabp3 knockout (KO) mice showed decreased social memory and novelty seeking, and Fabp7 KO mice displayed hyperactive and anxiety-related phenotypes, while Fabp5 KO mice showed no apparent phenotypes." (PMID 25027319, 2014).
astrocytoma (2 papers, 2015 to 2020). "CRABP II and FABP5 were expressed, respectively, in 58.3% (7/12) and 75% (9/12) of grade I astrocytomas, 86.7% (26/30) and 63.3% (19/30) of Grade II, 64.5% (20/31) and 71% (22/31) of Grade III, and 63.6% (7/11) and 45.5% (5/11) in Grade IV." (PMID 25797252, 2015). "The expression patterns of CRABP-II and FABP5 in the four grades of astrocytomas were analyzed using tissue microarray-based immunohistochemical staining." (PMID 25797252, 2015). "For this reason, CRABP-II and FABP5 expression patterns and their ratios in different grades of astrocytomas were profiled immunohistochemically." (PMID 25797252, 2015). "Taken together, the current study demonstrates variable expression patterns of CRABP-II and FABP5 among the four astrocytoma grades." (PMID 25797252, 2015). "CRABP-II and FABP5 were expressed to varying degrees by the 84-astrocytoma cases examined." (PMID 25797252, 2015). "CRABP II and FABP5 were expressed differently within the four-astrocytoma grades." (PMID 25797252, 2015). "It was revealed that CRABP-II and FABP5 were expressed in four forms as CRABP-II−/FABP5−, CRABP-II−/FABP5+, CRABP-II+/FABP5− and CRABP-II+/FABP5+ in the different grades of astrocytomas and the expression was unrelated to the tumor grade." (PMID 25797252, 2015). "The staining patterns or labeling densities of CRABP-II and FABP5 in the four grades of astrocytomas were analyzed and compared with their surrounding noncancerous counterparts." (PMID 25797252, 2015).
brain cancer (2 papers, 2021 to 2025). A primary or metastatic malignant neoplasm affecting the brain. "In addition, specific FABP subtypes exhibit tissue- and context-dependent functions, with FABP4, FABP5, FABP6, and FABP7 being the most extensively studied in breast, liver, colorectal, and brain cancers." (PMID 40717587, 2025).
brain infarction (2 papers, 2021 to 2026). Tissue necrosis in any area of the brain, including the cerebral hemispheres, the cerebellum, and the brain stem. "RSV downregulates FABP5 expression in cerebral infarction tissues and potentially mediates the AMPK-related pathways to ameliorate neuronal apoptosis." (PMID 41907041, 2026). "In this study, we demonstrated that MF6 decreased brain infarction volumes and neurological deficits in mice subjected to tMCAO and reperfusion by inhibiting FABP3, FABP5 and FABP7 expression in the brain." (PMID 34068550, 2021).
Cirrhosis (2 papers, 2009 to 2023). A chronic disorder of the liver in which liver tissue becomes scarred and is partially replaced by regenerative nodules and fibrotic tissue resulting in loss of liver function. "In this study, the expressional levels of SCD2, FABP4 and FABP5 increased during the process from cirrhosis to metastasis in rat model, suggesting that an alteration of the fat metabolism occurred in hepatocarcinogenesis of rat model." (PMID 19638242, 2009).
cognitive deficits (2 papers, 2021 to 2025). "Their studies demonstrated that deletion of FABP5 resulted in cognitive deficits, which were reversed by THC inhalation." (PMID 41333412, 2025). "On the other hand, another study indicated cognitive impairments in learning and memory in FABP5 knockout mice, which are related to diminished peroxisome proliferator-activated receptor (PPAR) β/δ activation by arachidonic acid." (PMID 34067791, 2021). "Furthermore, a recent study also indicated that FABP5 is localized in the BBB and is essential for maintaining brain endothelial cell uptake of DHA, and FABP5 knockout mice suggested obvious cognitive deficits associated with decreased DHA levels in the brain." (PMID 34067791, 2021).
colorectal tumor (2 papers, 2024 to 2025). "In contrast, the colorectal tumor milieu—characterized by high immune cell infiltration and distinct microbial and metabolic profiles—may shift FABP5’s function toward tumor-suppressive pathways, such as mTOR-dependent autophagy." (PMID 40717587, 2025). "Another two macrophage clusters with a lipid-associated (LA) metabolism transcriptional signature, including genes such as FABP5, LPL, and LIPA, named RTM_LA (n = 3569) and Mac_LA (n = 1249), were found enriched in breast, lung, and colorectal tumors." (PMID 38972873, 2024).
Erythema (2 papers, 2017 to 2023). Redness of the skin, caused by hyperemia of the capillaries in the lower layers of the skin. "Skin-stripping FABP5 did not correlate with PASI, but was statistically associated with total erythema, induration and desquamation scores." (PMID 27864793, 2017).
esophageal cancer (2 papers, 2021 to 2024). A primary or metastatic malignant neoplasm involving the esophagus. "According to relevant literature reports, FABP5 can reprogram the fatty acid metabolism of tumors to promote tumor growth, although there is limited research on FABP5 in esophageal cancer." (PMID 38277205, 2024). "The biological relationship between CRABP2 and FABP5 can be used as a target for the treatment of esophageal cancer remains to be further studied by this group." (PMID 34632074, 2021).